EPHB4 (EPH receptor B4)
Description:
Receptor tyrosine kinase which binds promiscuously to transmembrane ephrin-B family ligands residing on adjacent cells, leading to contact-dependent bidirectional signaling into neighboring cells. The signaling pathway downstream of the receptor is referred to as forward signaling while the signaling pathway downstream of the ephrin ligand is referred to as reverse signaling. Together with its cognate ligand/functional ligand EFNB2, it is involved in the regulation of cell adhesion and migration, and plays a central role in heart morphogenesis, angiogenesis and blood vessel remodeling and permeability. EPHB4-mediated forward signaling controls cellular repulsion and segregation from EFNB2-expressing cells. Phosphorylates inactive tyrosine-protein kinase EPHB6 which promotes interaction of EPHB6 with SH2 domains, allowing it to recruit SH2 domain-containing signaling adapters.
Synonyms: HTK; MYK1; TYRO11; CMAVM2; HFASD; LMPHM7
Tractability: Small molecule: an approved drug acts on it; a structure with a bound ligand is known; a high-quality ligand is known; it has a high-quality binding pocket; it belongs to a druggable protein family. Antibody: UniProt places it where antibodies can reach, with high confidence; its Gene Ontology location is reachable by antibodies, with high confidence; UniProt predicts a signal peptide or a membrane-spanning region. PROTAC: it is named in the literature on targeted protein degradation; ubiquitination databases record sites on it; a small molecule that binds it is known.
Target class: Tyrosine protein kinase Eph family; Protein Kinase; TK protein kinase group; Kinase; Enzyme
Chemical probes: AZ12672857
Gene: Protein-coding gene on chromosome 7 (100,802,563 to 100,827,555, reverse strand). Ensembl gene ENSG00000196411.
Subcellular location: Cell membrane
Pathways (Reactome):
Developmental Biology: EPH-Ephrin signaling; EPH-ephrin mediated repulsion of cells; EPHB-mediated forward signaling; Ephrin signaling
Gene Ontology:
Molecular function: ephrin receptor activity; protein binding; transmembrane receptor protein tyrosine kinase activity; ATP binding; protein kinase activity; protein tyrosine kinase activity
Biological process: angiogenesis; cell adhesion; cell migration involved in sprouting angiogenesis; ephrin receptor signaling pathway; heart morphogenesis; cell surface receptor protein tyrosine kinase signaling pathway
Cellular component: extracellular exosome; plasma membrane; cytosol; extracellular region; receptor complex; membrane
Genetic constraint (gnomAD): Loss-of-function variants: 48 observed, 94.64 expected, observed/expected ratio (o/e) 0.51, 90% interval 0.4 to 0.64. The upper end of that interval is the gene's LOEUF score, 0.64, which puts it in group 2 of 6, group 1 being the genes least tolerant of losing a copy. Missense variants: 1,059 observed, 1,221.2 expected, observed/expected ratio (o/e) 0.87, 90% interval 0.82 to 0.91. Synonymous variants: 553 observed, 518.94 expected, observed/expected ratio (o/e) 1.07, 90% interval 0.99 to 1.14.
Gene-disease validity (ClinGen):
ClinGen rates the evidence that EPHB4 causes each of these diseases.
EPHB4-associated vascular malformation spectrum (autosomal dominant): Definitive. Any vascular malformation in which the cause of the disease is a variation in the EPHB4 gene.
Homologues: Orthologues: chimpanzee EPHB4 (100% identical), macaque EPHB4 (99% identical), dog EPHB4 (97% identical), guinea pig EPHB4 (95% identical), rat Ephb4 (93% identical), mouse Ephb4 (93% identical), pig EPHB4 (91% identical), rabbit EPHB4 (89% identical), tropical clawed frog ephb4 (60% identical), zebrafish ephb4b (59% identical). Paralogues in human: EPHB3 (57% identical), EPHB1 (55% identical), EPHB2 (55% identical), EPHA4 (50% identical), EPHA5 (49% identical), EPHA6 (49% identical), EPHA7 (48% identical), EPHA3 (48% identical), EPHA8 (46% identical), EPHA2 (45% identical), EPHA1 (40% identical), EPHA10 (39% identical), and 41 more.
Diseases named in the same sentence as EPHB4 in open-access papers:
EPHB4 is named in the same sentence as 175 diseases in open-access papers, as found by Europe PMC text mining. Sharing a sentence is not in itself a finding about the gene and the disease. The quoted sentences say what the papers report.
breast carcinoma (41 papers, 2005 to 2025). "For example, a kinase-deficient EphB4 mutant was still capable of increasing breast cancer cell growth." (PMID 31949258, 2020). "Notably, EphB4 knockout cancer cells had low expression of Nefl, which has been shown to be associated with nodal spread and poor prognosis in breast cancer patients." (PMID 39091728, 2024). "Similar to EphA2, EphB4 has been implicated in breast cancer in numerous studies." (PMID 33430066, 2021). "In breast cancer, for instance, EphB4–ephrin-B2 forward signaling exerts tumor-suppressive effects, whereas ligand-independent EphB4 activity can promote tumor growth and invasion depending on the cellular context." (PMID 41009819, 2025). "EphB4 has been reported to be a membrane protein expressed in breast cancer, head and neck cancer, and colorectal cancer, although its expression in normal tissues is limited." (PMID 40076777, 2025). "The knockdown of EphB4 in breast cancer cells has been shown to inhibit integrin-mediated cell adhesion, spreading and migration." (PMID 38811954, 2024). "EphB4, in breast cancer cells, activates an anti-oncogenic Abl-Crk pathway, inhibiting cell viability, proliferation, motility, and invasion, and downregulates the pro-invasive matrix metalloprotease, MMP-2." (PMID 38811954, 2024). "EphA2 and EphB4 have been the most extensively studied in relation to breast cancer, although other Eph receptors have also been identified." (PMID 36830852, 2023). "EphB4 induces antioncogenic signalling in breast cancer cells that involves Abl tyrosine kinase and the Crk adaptor protein." (PMID 36830852, 2023). "The best characterised Eph receptors in breast cancer are EphA2 and EphB4, but there are also others that have been found to play a role." (PMID 33430066, 2021). "EphB6 signaling, known to suppress breast cancer cell aggressiveness by interacting with EPHB4 and interfering with EPHB4 action, was repressed by Pparγ1 in ErbB2 mammary tumors." (PMID 33946495, 2021). "When stimulated by its preferred ligand, ephrin-B2, EphB4 behaved as a tumour suppressor in a mouse xenograft model of breast cancer." (PMID 33430066, 2021). "In MCF-7 breast cancer cells, on the other hand, EphB4 displayed pro-oncogenic effects, via ephrin-B2-mediated activation of the extracellular signal-regulated kinase (ERK) pathway, which has been linked to the promotion of protein phosphatase." (PMID 33430066, 2021). "Our group has previously shown EphA2 hyperphosphorylation in esophageal cancer based on cell line phosphotyrosine profiling data, whereas EphA2 and EphB4 have been upregulated in breast cancer." (PMID 34298619, 2021). "Existing evidence also showed that EphB4 was expressed on the surface of breast cancer cells that promote angiogenesis in tumor xenografts by activating Ephrin-B2 reverse signaling in the vasculature, thus increasing tumor growth." (PMID 32733636, 2020). "In the present study we evaluated EphB4 in breast cancer specimen using two TMAs consisting of in total 1329 patients with 100 complete T/N tissue pairs." (PMID 32751634, 2020). "Our data on 100 T/N sets indicate that for the majority of breast cancers EphB4 would be an appropriate target." (PMID 32751634, 2020). "Based on immunohistochemical results from two relatively large cohorts of in total 1329 patients EphB4 shows potential as a target for image-guided breast cancer surgery." (PMID 32751634, 2020). "EphB4 is also reported to be abundantly present in a variety of solid tumors, including colorectal cancer, prostate cancer, gastric cancer, and breast cancer, suggesting a common mechanism in carcinogenesis." (PMID 32751634, 2020). "Among EphB receptors, EphB4 has been shown to be upregulated as well as downregulated in breast cancer cells, and knockdown of EphB4 inhibits tumor cell viability." (PMID 29682554, 2018).
breast carcinoma (continued). "Among the family members, EPHA2 and EPHB4 are the most studied in breast cancer and additionally EPHA4, EPHA7 and EPHB6 emerged as promising clinical candidates in an expression profile of the individual EPH and ephrin family members." (PMID 26870995, 2016). "For instance, the adhesive ephrin type-B receptor 4 (EPHB4) inhibits MDA-MB 435 breast cancer cell invasion through an ABL-CrkII signaling pathway and ABL activation can inhibit TGFβ oncogenic signaling in the murine breast cell line 4T1." (PMID 25803821, 2015). "A monoclonal antibody which specifically targets this identified extracellular epitope of EphB4 significantly reduced breast cancer xenograft growth in vivo confirming that EphB4 is a useful target for ligand-mimicking antibody-based anti-cancer therapies." (PMID 25831049, 2015). "In breast cancer cell lines, EphB4 exogenous overexpression reduces integrin β1 expression resulting in increased migration in a ligand-independent manner." (PMID 25886373, 2015). "Bioinformatic analysis of gene expression data across cancers indicated overexpression of EPHB4 and MTHFD2 in breast cancer and high expression associated with poor clinical characteristics." (PMID 23295955, 2013). "In breast cancer, elevated RNA expression of EphA4 had significant prognostic value, as did EphA2, EphA7, and EphB4." (PMID 23738943, 2013). "Based on these results and the fact that EPHB4 had already been described as a target for breast cancer treatment, MTHFD2 was chosen for more detailed functional studies." (PMID 23295955, 2013). "EphB4 knockdown inhibited breast cancer survival, migration, and invasion in vitro and tumor growth in a xenograft model in vivo." (PMID 21935409, 2011). "These analyses confirmed the relevance of EphA2 and EphB4 to human breast cancer progression, and uncovered significant correlations for EphA4, EphA7, and EphB6, which were previously under-investigated in breast cancer." (PMID 21935409, 2011). "The TNYL-RAW peptide has been shown to inhibit EphB4 tyrosine phosphorylation (activation) induced by ephrin-B2 in cultured MCF7 breast cancer cells and human umbilical vein endothelial cells (HUVECs)." (PMID 22194865, 2011). "As LCA showed to be a promiscuous ligand of EphA and EphB receptor subfamilies wetested LCA activity against EphB4 phosphorylation on T47D breast cancer cellsinduced by 3 μg/ml ephrinB2-Fc, preclustered with 0.3 μg/ml of IgGFc fragment." (PMID 21479221, 2011). "It is assumed, that the kinase inhibitor imatinib can counteract the anti-oncogenic effects of EphB4 agonists in breast cancer." (PMID 20224755, 2010). "More recently, siRNA and antisense studies have confirmed that EPHB4 has an essential role in many processes that contribute to cancer cell survival and spread in several cancers including breast cancer." (PMID 19500345, 2009). "Accordingly, high levels of EphB4 expression in breast cancer cell lines was found to be often accompanied by low expression of its ligand, ephrin-B2, and this allows for signalling via ligand-independent pathways and evasion of EphB4’s tumour-suppressing effects." (PMID 33430066, 2021). "Similarly, a previous study demonstrated that an EPHRIN B2-induced EPHB4 signaling cascade, mediated by the Abl-Crkl pathway, resulted in apoptosis in mammary carcinoma." (PMID 33816783, 2021). "In this study we investigated the applicability of EphB4 as a target for breast cancer imaging." (PMID 32751634, 2020). "EphA2 and EphB4 are the two most extensively studied receptors in breast carcinomas." (PMID 29682554, 2018). "Independent studies reported EphB4 and EphB2 overexpression in human breast cancer." (PMID 21935409, 2011). "We evaluated protein expression of EphA2, EphA4, EphA7, EphB4, and EphB6 in human breast cancer tissue microarrays (TMA) in which we could distinguish expression in tumor epithelium from stromal components, including endothelium." (PMID 21935409, 2011).
breast carcinoma (continued). "Expression of truncated, soluble EphB4 receptor in breast cancer cells in a mouse xenograft model (with ephrinB2 ligand primarily expressed in the vasculature) increased tumor angiogenesis, suggesting that soluble EphB4 promotes tumor growth by stimulating angiogenesis through ephrinB2 signaling." (PMID 20224755, 2010). "Similarly, EphB4 levels are also elevated in human breast cancer." (PMID 21935409, 2011). "Other studies investigating the effects of EphB4/ephrinB2 on tumor microvasculature, tumor growth, and survival of tumor cells indicated that EphB4 could act as a survival advantage in head and neck squamous cell carcinoma and in breast cancer, respectively." (PMID 20224755, 2010). "In addition, we have shown that EphB4 upregulates several antiapoptotic proteins, particularly bcl-xl, in bladder and breast cancer cells, thus suggesting other sites of action by which EphB4 may inhibit tumour cell apoptosis." (PMID 17353927, 2007). "In breast cancer, the expression frequency of CLDN1 is low, but in addition to EphB4, LAT1 is expressed at high frequencies." (PMID 40076777, 2025). "Investigation of the role of the EPH/ephrin system in breast cancer has mainly focused on the receptors EPHA2, EPHB4, and EPHB6." (PMID 35204461, 2022). "In preclinical breast cancer models, the IGF1/IGF1R/Akt axis sustained mRNA expression of EphB4, thereby promoting cell proliferation and migration responses, which were sentitive to the PI3K inhibitor LY294002." (PMID 34440844, 2021). "Hitherto several groups have studied the connections between the EPH family and breast cancer where EPHA2 and EPHB4 are two of the most investigated EPH receptors with potential clinical relevance." (PMID 26870995, 2016). "Interestingly, our previous work showed that the EPHB6 receptor suppresses aggressiveness of breast cancer cells by interacting with EPHB4 and interfering with EPHB4 action, which implies that EPHB6 may also enhance the DR4- or DR5- mediated apoptotic response." (PMID 27788485, 2016). "Their expression in breast cancer has been investigated using cell lines, animal models, and human tissue samples, and correlated with patients’ prognosis EPHA2, EPHB4, and EPHB6 are the receptors most extensively studied so far." (PMID 35204461, 2022). "Our findings support EphB4 as a good target for FIGS, even for early stage breast cancer patients." (PMID 32751634, 2020). "The mechanisms that drive EphB4 over-expression in cancer cells have not been determined although EphB4 itself was recently reported to regulate the estrogen receptor α and vimentin in breast cancer." (PMID 25831049, 2015). "For instance, TNYL-RAW has been recently used to demonstrate that ephrin-B2 has effects in endothelial cells that are independent of interaction with EphB4 and that EphB4 has effects in breast cancer cells that are independent of interaction with ephrin-B2." (PMID 22194865, 2011). "In the main part of this study, the expression of the panel of 5 RT-PCR markers (TACSTD1, EPHB4, ELF3, EGFR, and MGB1) was determined after immunobead enrichment of circulating epithelial cells in blood samples obtained from 56 early stage breast cancer patients." (PMID 19500345, 2009). "Immunomagnetic enrichment of circulating tumour cells followed by RT-PCR (immunobead RT-PCR) with a panel of five epithelial specific markers (ELF3, EPHB4, EGFR, MGB1 and TACSTD1) was used to screen for circulating tumour cells in the peripheral blood of 56 breast cancer patients." (PMID 19500345, 2009). "Small-interfering-RNA (siRNA)-mediated knockdown of EphB4 expression resulted in a dose-dependent decrease in cell survival, increased apoptosis, and a heightened sensitivity to the tumour-necrosis-factor-related apoptosis-inducing ligand (TRAIL) in breast cancer." (PMID 36830852, 2023). "Therefore, we have focused on EphB4 as an alternative target, especially for Her-2 negative breast cancer patients." (PMID 32751634, 2020).
breast carcinoma (continued). "Moreover, survival of patients with breast and ovarian cancers was reduced with increased expression level of EphB4 but not of EpoR, and Epo treatment further reduced the survival chances of breast cancer patients with tumors that express high levels of EphB4." (PMID 29393890, 2018). "The screens were done in metastatic breast cancer cells expressing vimentin at high levels and three novel vimentin regulators - WAS/WASL interacting protein family member 2 (WIPF2), methylenetetrahydrofolate dehydrogenase 2 (MTHFD2) and ephrin type-B receptor 4 (EPHB4) were identified." (PMID 23295955, 2013). "It was not clear if this was an effect of EphB4 on metastasis or a result of accelerated tumour growth but these results clearly implicate over-expression of EphB4 in tumour growth and/or establishment of the invasive phenotype in the adult mammary tumours." (PMID 16171530, 2005). "Interestingly, although EPHB4 inhibits Ras-MAPK signaling in EC and EC proliferation through a RASA1-depednedent mechanism, in other cell types such as hepatic stellate cells or MC7 breast cancer cells, EPHB4 activates the Ras-MAPK pathway resulting in increased proliferation." (PMID 37259315, 2023). "In prostate cancer 22Rv1 and breast cancer MCF7-10A cells, EPHB4 suppressed cancer cell growth via EPHB4/EFB2 signalling pathway in the presence of EFNB2; however, EPHB4 promoted cancer cell growth in the absence of EFNB2." (PMID 28035996, 2016).